FLG (filaggrin)
Description:
Aggregates keratin intermediate filaments and promotes disulfide-bond formation among the intermediate filaments during terminal differentiation of mammalian epidermis.
Synonyms: FLG1; FLG-1; ATOD2
Tractability: Antibody: its Gene Ontology location is reachable by antibodies, with high confidence.
Gene: Protein-coding gene on chromosome 1 (152,302,165 to 152,325,239, reverse strand). Ensembl gene ENSG00000143631.
Subcellular location: Cytoplasmic granule
Subcellular location (Human Protein Atlas): Cytoplasmic bodies
Pathways (Reactome):
Developmental Biology: Differentiation of Keratinocytes in Interfollicular Epidermis in Mammalian Skin; Formation of the cornified envelope
Gene Ontology:
Molecular function: protein binding; structural constituent of skin epidermis; calcium ion binding; structural molecule activity; transition metal ion binding
Biological process: cornification; establishment of skin barrier; keratinocyte differentiation
Cellular component: cornified envelope; cytoplasmic ribonucleoprotein granule; extracellular matrix; keratohyalin granule; nucleus; cytosol
Genetic constraint (gnomAD): Loss-of-function variants: 8 observed, 5.31 expected, observed/expected ratio (o/e) 1.51, 90% interval 0.83 to 1.93. That is too few expected variants to judge how well the gene tolerates losing a copy. Missense variants: 7,539 observed, 4,618.1 expected, observed/expected ratio (o/e) 1.63, 90% interval 1.6 to 1.66. Synonymous variants: 2,535 observed, 1,746.1 expected, observed/expected ratio (o/e) 1.45, 90% interval 1.4 to 1.5.
Homologues: Orthologues: chimpanzee FLG (57% identical), dog FLG (22% identical), mouse Flg (3% identical). Paralogues in human: HRNR (18% identical), FLG2 (17% identical), RPTN (5% identical).
Diseases named in the same sentence as FLG in open-access papers:
FLG is named in the same sentence as 179 diseases in open-access papers, as found by Europe PMC text mining. Sharing a sentence is not in itself a finding about the gene and the disease. The quoted sentences say what the papers report.
atopic dermatitis (279 papers, 2007 to 2026). "Background/Objective: Ichthyosis vulgaris (IV) is a genodermatosis caused by heterozygous, homozygous, or compound heterozygous variants in the filaggrin (FLG) gene on chromosome 1q21, which also predispose individuals to atopic dermatitis." (PMID 40282340, 2025). "The most common susceptibility gene for psoriasis is HLA-Cw*0602, located on PSORS1 at 6p21, while null mutations in the filaggrin (FLG) gene represent the strongest genetic risk factor for developing atopic dermatitis." (PMID 39859462, 2025). "Patients respond differently to specific strains due to a variety of factors, including their unique microbiome, age, disease progression, comorbidities, and genetic background (such as filaggrin mutations in atopic dermatitis)." (PMID 41304102, 2025). "Atopic dermatitis is characterized by an impaired skin barrier function due to filaggrin gene mutations." (PMID 40568299, 2025). "Among the top signals, they identified FLG, the gene encoding filaggrin, a key epidermal barrier protein and a well-known risk factor for atopic dermatitis, as a candidate gene in AD." (PMID 41465136, 2025). "The disease nucleotide decreased FLG expression, indicating that FLG is a rs72696969 target gene and that the atopic dermatitis risk daSNV down-modulates expression of this differentiation gene essential for normal barrier function." (PMID 40998781, 2025). "Loss-of-function mutations in FLG, a protein crucial for maintaining epidermal integrity, are linked to atopic dermatitis and increased food allergen sensitization." (PMID 40290033, 2025). "A study analyzing filaggrin knockdown in human differentiated keratinocytes showed that filaggrin loss-of-function (LOF) mutations are strongly associated with atopic dermatitis." (PMID 40225445, 2025). "Risk factors for the development of atopic dermatitis include intrinsic factors such as loss of function mutations in FLG, the gene encoding for filaggrin." (PMID 39721985, 2025). "Operating downstream of the Wnt/β‐catenin signalling cascade in both mice and Drosophila, OVOL1 has also been implicated in the suppression of atopic dermatitis through modulation of FLG expression in mouse keratinocytes." (PMID 40437660, 2025). "Filaggrin deficiency in humans is associated with atopic dermatitis and leads to changes in skin microbiota composition relative to that in healthy controls." (PMID 40164684, 2025). "Other genetic findings included two pathogenic variants associated with atopic dermatitis (FLG, C0120), a VUS for familial Mediterranean fever (MEFV, C037) and one somatic pathogenic variant for myeloproliferative disorder (JAK2, C123)." (PMID 40455168, 2025). "Atopic dermatitis is caused by either a deficiency of filaggrin (an epidermal structural protein) or environmental factors." (PMID 40164684, 2025). "In infants with atopic dermatitis, genetic factors such as filaggrin (FLG) mutations or inflammation compromise epidermal integrity, allowing allergens to penetrate and skew immune responses toward Th2 pathways with enhanced IgE production." (PMID 41010790, 2025). "Loss-of-function mutations in the FLG gene, which encodes filaggrin, are among the main risk factors for developing atopic dermatitis." (PMID 41002407, 2025). "Researchers are looking into using filaggrin inducers and protease inhibitors to treat the underlying causes of atopic dermatitis and Netherton syndrome." (PMID 40734872, 2025). "Patients with both filaggrin mutations and colonization of S. aureus exhibit higher severity scores in the Scoring Atopic Dermatitis (SCORAD) assessment, indicating a more severe manifestation of AD." (PMID 40697652, 2025). "Several genes, including FLG which is associated with atopic dermatitis and asthma, showed converging evidence from both rare and common variants." (PMID 39009607, 2024).
atopic dermatitis (continued). "Loss-of-function mutations in the filaggrin gene have been identified as significant contributors to the pathogenesis of atopic dermatitis in European populations." (PMID 38938453, 2024). "Loss-of-function mutation of filaggrin has been described in atopic dermatitis and is associated with a decreased skin barrier function." (PMID 40225748, 2024). "Loss-of-function mutations (LoF) in the filaggrin structural protein are considered the most significant genetic predisposing factor for the onset of atopic dermatitis." (PMID 38938453, 2024). "Severe atopic dermatitis has been linked to deficiencies in the filaggrin (FLG) protein or antimicrobial peptides." (PMID 39564133, 2024). "Previous studies have reported swimming, atopic dermatitis, and filaggrin (FLG) gene mutations as risk factors for molluscum contagiosum (MC) infection." (PMID 38414183, 2024). "Mutations that inhibited the FLG gene predisposed to both ichthyosis vulgaris and atopic dermatitis." (PMID 38907248, 2024). "Loss-of-function (LoF) variants in the filaggrin (FLG) gene are the strongest known genetic risk factor for atopic dermatitis (AD), but the impact of these variants on AD outcomes is poorly understood." (PMID 38564302, 2024). "Current research has discovered that mutations in the filaggrin gene are associated with skin-related diseases such as atopic dermatitis and psoriasis." (PMID 38790293, 2024). "Atopic dermatitis (AD) is a chronic inflammatory skin disease for which filaggrin (FLG) gene mutations are the strongest genetic risk factor." (PMID 38585273, 2024). "Atopic dermatitis, a skin condition, is influenced by various factors including genetic variables, such as loss-of-function mutations in the filaggrin gene (FLG), as well as environmental factors like climate, nutrition, and lactation." (PMID 38938453, 2024). "Defects in the CE cause skin pathologies; for example, mutations in filaggrin cause ichthyosis vulgaris and predispose to atopic dermatitis." (PMID 39373389, 2024). "These cytokines bind to their respective receptors and exert their effects via JAK-STAT signal transduction, causing downregulation of filaggrin gene expression and skin barrier dysfunction, playing a role in atopic dermatitis." (PMID 39360077, 2024). "Atopic dermatitis (AD) is a chronic inflammatory skin disease with rising prevalence, marked by eczematous lesions, itching, and a weakened skin barrier often tied to filaggrin gene mutations." (PMID 39766227, 2024). "The important role of filaggrin (FLG) in skin barrier function and maintaining skin hydration has been demonstrated by the strong association between the loss of function of FLG and atopic dermatitis." (PMID 39065574, 2024). "A similar mechanism involving impaired barrier function is seen in atopic dermatitis, though in this case, it is connected with filaggrin mutations." (PMID 39408857, 2024). "FLG loss-of-function mutations have been linked to a three- to fourfold higher risk of developing atopic dermatitis in meta-analyses." (PMID 36660532, 2023). "Normal and filaggrin(FLG)-deficient (predisposing factor for atopic dermatitis) hPSkCs were cultured on top of naïve human CD4+ T cells." (PMID 38136325, 2023). "For instance, IL-4 and IL-13, pathogenic for atopic dermatitis, and IL-17A, pathogenic for psoriasis, lead to a downregulation of filaggrin." (PMID 38132754, 2023). "Loss in filaggrin (either by environmental insults or genetic loss of function mutations) is typically associated with skin inflammation including atopic dermatitis." (PMID 37762646, 2023). "Reduced filaggrin expression is a significant risk factor for atopic dermatitis development; however, in our study all subjects, babies and adults, were classified as healthy individuals, free of any cosmetic skin conditions." (PMID 37374986, 2023).
atopic dermatitis (continued). "Nevertheless, FLG deficiency appear to remain the most widely established risk factors for atopic dermatitis with the greatest impact on skin barrier structure and function." (PMID 36904070, 2023). "FLG mutations are found in, at most, one-half of atopic eczema cases, even in the cohorts with the most severe cases." (PMID 36013110, 2022). "For instance, the expression of filaggrin is downregulated by the interleukins IL-4 and IL-13, which are pathogenic for atopic dermatitis, as well as by IL-17A, which is pathogenic for psoriasis." (PMID 36362566, 2022). "The FLG loss-of-function mutation is associated with ichthyosis vulgaris, atopic dermatitis, inflammatory dermatosis, and inflammation dysregulated diseases such as asthma and allergy." (PMID 36046250, 2022). "One associated locus is syntenic to the major genetic risk locus (Filaggrin locus) in human atopic dermatitis." (PMID 36482174, 2022). "An abnormal catabolism of filaggrin occurs in atopic dermatitis and has been suggested as a cause for an abnormal skin barrier." (PMID 35878340, 2022). "The most cited pathogenesis-related article was published in 2006, titled “Common loss-of-function variants of the epidermal barrier protein filaggrin are a major predisposing factor for atopic dermatitis”." (PMID 36532008, 2022). "Filaggrin is a protein that maintains the epithelial barrier of the nose and skin, and filaggrin defects have previously been associated with spontaneous atopic dermatitis, acting as disease biomarkers, and with secondary lung inflammation in mice." (PMID 36482106, 2022). "Null mutations within the filaggrin (FLG) gene are established genetic risk factors for atopic dermatitis." (PMID 39108470, 2022). "Keratosis pilaris (KP) is a common inherited disorder which has been associated with filaggrin (FLG) loss‐of‐function (LoF) mutations, atopic dermatitis (AD), and ichtyosis vulgaris." (PMID 35616138, 2022). "Deficiency in a principal epidermal barrier protein, filaggrin (FLG), is associated with multiple allergic manifestations, including atopic dermatitis and contact allergy to nickel." (PMID 35359602, 2022). "Filaggrin loss-of-function mutations cause skin barrier damage and IgE sensitization in patients with atopic dermatitis." (PMID 34946332, 2021). "In this study, the association between loss-of-function variants in the FLG gene and other allergic manifestations, in particular food allergy, was evaluated in an Italian pediatric population affected by atopic dermatitis." (PMID 33440636, 2021). "Several genetic variables have also been associated with the development of atopic dermatitis and food allergies: Filaggrin (FLG) is an important protein for the aggregation of filaments within the epidermis." (PMID 34820047, 2021). "Several studies have demonstrated that FLG loss-of-function mutations are associated with atopic eczema and AD phenotype in FLG null-mutation has an earlier onset, greater severity, and increased persistence." (PMID 34943362, 2021). "Common loss-of-function (LOF) variants in the filaggrin (FLG) gene are an established susceptibility factor for chronic eczema (atopic dermatitis; AD)." (PMID 35052551, 2021). "The etiology of atopic dermatitis is marginally understood in spite of the number of predisposing factors, above all, mutations in the Filaggrin gene (FLG)." (PMID 33440636, 2021). "FLG mutation, associated with ichthyosis vulgaris and atopic eczema, was first identified as a biomarker linked to a poor prognosis in glioma." (PMID 34307451, 2021). "Filaggrin mutations have been reported as one of the most documented risk factors for atopic dermatitis in people; thus, it was natural to address this issue in dogs." (PMID 34357916, 2021). "Discovery of inactivating mutations in filaggrin protein has shed new light on atopic dermatitis mechanism, which has been implicated in sever atopic dermatitis pathology." (PMID 33937097, 2021).
atopic dermatitis (continued). "The strongest genetic predisposing factor to atopic dermatitis is loss-of-function mutations in the filaggrin gene, which is essential for skin barrier function." (PMID 34946332, 2021). "This study aimed to analyze the gender-specific association of the filaggrin (FLG) gene polymorphisms with atopic dermatitis (AD) in Caucasians from the central region of Russia." (PMID 34882715, 2021). "Genetic abnormalities related to filaggrin are known to be strongly associated with atopic dermatitis." (PMID 32326002, 2020). "Filaggrin gene mutations are the most known genetic factor, but numerous environmental and immunological factors affect the manifestation and course of atopic dermatitis." (PMID 32218222, 2020). "With the discovery that mutation of the epidermal gene filaggrin predisposes one to the occurrence of allergic dermatitis and asthma, the connection was explained between dermatitis and allergic diseases." (PMID 32218222, 2020). "Mutations of the filaggrin gene (FLG) are associated with allergen sensitization and allergic diseases like atopic dermatitis (AD), allergic rhinitis, food allergy (FA), and asthma." (PMID 32536107, 2020). "Loss-of-function mutations in FLG, which encodes filaggrin, have been verified in atopic dermatitis." (PMID 32054030, 2020). "Filaggrin is widely studied in the context of atopic dermatitis, because loss-of-function mutations of its encoding FLG gene are a major genetic risk factor for this common skin disease (also known as eczema) (OMIM #605803 and #135940)." (PMID 33228136, 2020). "Filaggrin gene defects are known to increase the risk of allergic sensitization, atopic eczema and AR." (PMID 33133517, 2020). "Even patients with atopic dermatitis who do not harbor genetic defects related to filaggrin can have decreased filaggrin levels later, suggesting that filaggrin is closely related to the mechanism underlying the development of atopic dermatitis." (PMID 32326002, 2020). "In particular, filaggrin deficiency has been reported to cause atopic dermatitis at an early age, increase the sensitivity and severity of allergies, and increase infection vulnerability." (PMID 32326002, 2020). "Studies on atopic dermatitis reveal damages to filaggrin and deficiency of free fatty acids in the lipid structure as the main causes of diseases." (PMID 31780876, 2019). "Several loci were disease-specific, such as Filaggrin (FLG) for atopic dermatitis, or a SNP near IL18R1, where the effect allele was increased in asthma and hayfever, but not atopic dermatitis." (PMID 31921716, 2019). "Some common skin barrier diseases, such as atopic dermatitis (AD) and ichthyosis vulgaris (IV), are connected with a filaggrin deficiency like filaggrin gene mutations." (PMID 31480216, 2019). "In a subanalysis using data from the 1958 cohort only, genetic mutations previously associated with atopic eczema, including filaggrin-null mutations, and allergen-specific IgE were more common among those with childhood-onset disease." (PMID 31260715, 2019). "This progression depends on various factors, such as the presence of filaggrin mutations and the time of onset, severity, and control of atopic dermatitis, which were found to be related to a higher risk for the development of AR." (PMID 30029503, 2018). "Loss-of-function variants of the filaggrin mutation result in an impaired epidermal barrier function and have been shown to be a risk factor for the development of atopic dermatitis, allergies, and asthma." (PMID 30524933, 2018). "The first study established a relationship between MAP17 and filaggrin, a cornified envelope-associated protein usually downregulated in inflammatory skin diseases such as atopic dermatitis." (PMID 29650022, 2018). "The most well-known skin barrier protein is FLG, whose loss-of-function in mutation studies have been linked to a permeability barrier abnormality and atopic dermatitis." (PMID 30373163, 2018).